IGFBP2 (insulin like growth factor binding protein 2)
Diseases named in the same sentence as IGFBP2 in open-access papers (continued):
Sharing a sentence is not in itself a finding about the gene and the disease.
IGFBP2 also shares sentences with these, for which no sentence is quoted: autism (16 papers); developmental delay (12); Angelman syndrome (11); idiopathic pulmonary fibrosis (7); pulmonary hypertension (5); autism spectrum disorder (4); dyslexia (4); Intellectual disability (4); Microdeletion Syndrome (4); pneumonia (4); and language delay (3); Ataxia (3); chronic heart failure (3); congenital heart disease (3); ependymoma (3); Ewing sarcoma (3); learning disorders (3); 22q11.2 deletion syndrome (2); acute myeloid leukemia (2); acute respiratory distress syndrome (2); aortic valve stenosis (2); Attention Deficit Hyperactive Disorder (2); brain injury (2); cardiomyopathy (2); cholangiocarcinoma (2); chronic hepatitis C (2); clear cell carcinoma (2); cognitive decline (2); communicable diseases (2); diffuse astrocytoma (2).
A further 124 diseases each share a sentence with IGFBP2 in 2 papers or fewer.